EGFR (epidermal growth factor receptor)
Diseases named in the same sentence as EGFR in open-access papers (continued):
Sharing a sentence is not in itself a finding about the gene and the disease.
tumor (continued). "The anti-tumour efficacy of these treatments, administered alone and in combination for 2 weeks, was assessed in a VEGF-secreting human head and neck tumour cell line, CAL33, that highly expresses EGFR, established as xenografts (250 mm3) in nude mice." (PMID 18577994, 2008). "One of the tumours with high level HER2-neu amplification also stained intensily (3+) for EGFR without increased gene copy number." (PMID 18182111, 2008). "Moreover, analysis of multi-marker phenotypes of VEGF and EGFR expression identified a subgroup of VEGF-positive and EGFR-negative tumours that were highly resistant to treatment." (PMID 18182986, 2008). "The epidermal growth factor receptor (EGFR) tyrosine kinase family and the vascular endothelial growth factor (VEGF) superfamily are also well-known mediators of tumour cell proliferation and tumour-related angiogenesis, which can influence tumour biology and survival." (PMID 18231104, 2008). "Among 47 (48%) EGFR-negative primary tumours, 35 cases (74%) were positive for phosphorylated Akt and MAPK." (PMID 17579627, 2007). "In contrast, EGFR phosphorylation was barely detectable in HARA tumours, suggesting that the receptor was not active to the extent observed in the RWGT2 line." (PMID 17533397, 2007). "The expression of the first metagene was significantly elevated in tumours characterised by EGFR/ErbB2 overexpression (median: 1.109) compared to tumours without overexpression of EGFR or ErbB2 (median: 0.909) (P=0.004)." (PMID 17700572, 2007). "Other studies have shown that tumours co-expressing HER2 and EGFR have a poor prognosis suggesting that there is a relationship between these genes that drives pathogenesis and which may be targeted by gefitinib." (PMID 17626639, 2007). "Here, we studied the molecular mechanisms through which certain NSCLC tumor cell lines expressing mutant but not wild-type (WT) EGFR undergo apoptosis after treatment with the EGFR inhibitor gefitinib." (PMID 17973573, 2007). "Expression of EGFR at the cytoplasmic membrane was detected in 98.9% of tumours, with only one tumour being negative for EGFR expression." (PMID 17940507, 2007). "In the univariate analysis, EGFR expression correlated with response to chemotherapy, but not with age, gender, tumour site, and pathological differentiation." (PMID 17876336, 2007). "A 95% reference range is based on a normal distribution of the data, but serum EGFR (as with tumour markers in general) was not normally distributed in our control group." (PMID 17976236, 2007). "Tumour phenotype was identified as the most predictive parameter to discriminate between tumour samples with EGFR and/or ErbB2 overexpression and without EGFR and ErbB2 overexpression (β=18.039; P=0.038)." (PMID 17700572, 2007). "The fact that caveolin-1 is capable of suppressing the activity of many components of growth factor signalling pathways (e.g., the EGFR and components of the p42/44 MAPK pathway), makes it an attractive candidate tumour suppressor gene, and several lines of evidence support this proposal." (PMID 18949068, 2007). "Central to our model of inverse relationship between E-cadherin expression and EGFR, we were able to observe a lack of total and active EGFR expression in these tumours." (PMID 17406365, 2007). "Fifteen tumours (18.3%) showed no immunoreactivity (0% staining) for EGFR whereas 67 (81.7%) displayed either membranous or cytoplasmic positivity." (PMID 17311026, 2007). "Out of 13 samples with transcriptionally active NF-κB dimers, nine showed overexpression of EGFR and/or ErbB2 whereas out of 24 tumours without transcriptionally active NF-κB dimers only five showed overexpression of EGFR and/or ErbB2 (κ=0.476, P=0.004)." (PMID 17700572, 2007). "In this trial, the response rate among patients with tumours with amplification of EGFR was significantly higher than those without this characteristic (20% vs. 2%)." (PMID 17626639, 2007).
tumor (continued). "The selectivity of this technique was demonstrated by the identification of EGFR exon 19 deletions in the tumour populations of two patient samples but not the surrounding normal tissue remaining after microdissection." (PMID 17626639, 2007). "Response to cisplatin-based chemotherapy was 50 and 22% in patients with EGFR-positive and -negative tumours respectively (P=0.046)." (PMID 17876336, 2007). "It should be noted that Visscher and colleagues were unable to identify any correlations between EGFR and HRG expression in their primary tumour specimens; however, this may simply reflect the very small dataset (34 samples) used in the study." (PMID 17686159, 2007). "Likewise, 61% of patients with EGFR-positive tumours coexpressed VEGF, compared with 39% of those with EFGR-negative tumours (P=0.01)." (PMID 17609662, 2007). "Tumour tissues from GEFCAPI 01 are not available to study other molecular markers such as Her-2 amplification, c-Kit mutations, or EGFR mutations or amplification." (PMID 17876336, 2007). "There have also been reports of response to cetuximab/irinotecan in patients whose tumours do not express EGFR." (PMID 17242694, 2007). "A transient antitumor effect was also observed in tumor-bearing C/L858R mice (that express the erlotinib-sensitive EGFR mutant) that were similarly treated with 17-AAG (data not shown)." (PMID 17726540, 2007). "Of the 98 patients in the basal-like group, 45 co-expressed CK5/6 and EGFR, and 28 basal-like tumours expressed EGFR but not CK5/6." (PMID 17088909, 2006). "The phosphorylated state of EGFR and Akt might be clinical markers of Akt activation without ligand stimulation and increase specificity of gefitinib sensitivity and, therefore, may prove to be useful prognostic tests of tumor responsiveness, in addition to EGFR gene mutation and amplification." (PMID 17150102, 2006). "Epidermal growth factor receptor expression was confirmed by immunohistochemistry in tumours from 16 patients; no tumour tissue was available for EGFR analysis for one patient." (PMID 16622465, 2006). "It is well documented that tumor cells synthesize and respond to growth factors such as EGF, FGF, and PDGF, and that NSAIDs negatively regulate the EGF/PDGF pathway with evidence of crosstalk between COX-2 and EGFR." (PMID 17156488, 2006). "In an in vitro study, these two types of EGFR mutants demonstrated an enhanced TK activity in response to EGF and increased sensitivity to inhibition by TKI, although the biological activity between tumours with L858R and those with deletions was different." (PMID 16552419, 2006). "Gefitinib exerts its antitumor activity through the inhibition of EGFR tyrosine kinase; however, this activity does not significantly correlate with the level of EGFR expression by the tumor cell." (PMID 17150102, 2006). "Tumour EGFR expression has not proven to be a useful predictive marker of clinical response to EGFR-targeted therapies." (PMID 16622439, 2006). "Because we did not have the EGFR TKI response data for the Moffitt and Duke tumor specimens, we used pEGFR staining and mutation status as surrogates for EGFR signalling." (PMID 17096850, 2006). "Tumour expression of growth factor receptors of the HER family makes it possible to perform innovative therapeutic targeting as demonstrated by the development of clinically active drugs such as herceptin(®), cetuximab and EGFR tyrosine kinase inhibitors." (PMID 16940984, 2006). "In these studies, EGFR status was mostly determined by immunohistochemical staining of primary tumor samples rather than from recurrent or metastatic tumors." (PMID 17163999, 2006). "One cell line (SKRC-39) expressed high levels of eIF4E in the absence of upstream signalling, and one tumour (#12) showed a very similar biochemical pattern, with high eIF4E but no detectable EGFR or phospho-Erk." (PMID 15956968, 2005).
tumor (continued). "Gefitinib exerts antitumour activity through inhibition of EGFR-TK, but its antitumour activity is not significantly correlated with tumour cell EGFR expression." (PMID 15870831, 2005). "No specific tumour uptake was observed with either radioconjugate in the FaDu xenografts which express normal tissue levels of EGFR." (PMID 15770208, 2005). "As the EGFR expression level is not a good predictor of gefitinib sensitivity, EGFR expression status in tumours cannot be used to exclude patients from gefitinib trials." (PMID 15987464, 2005). "Biodistribution studies undertaken in BALB/c nude mice bearing de2-7 EGFR-expressing or amplified EGFR-expressing xenografts revealed that 125I-labelled ch806 failed to display any significant tumour retention." (PMID 15770208, 2005). "The over expressed wild-type EGFR and EGFRvIII are not independent predictors of median overall survival in the cohort of patients who did not undergo extensive tumor resection." (PMID 16236164, 2005). "This tumour showed no detectable Erk phosphorylation despite abundant Erk protein and no detectable EGFR." (PMID 15956968, 2005). "In addition, EGFR inhibitors have themselves been shown to exert antiangiogenic effects by reducing the expression of VEGF and other angiogenic factors by tumours, and inhibiting EGFR on tumour endothelium." (PMID 15928653, 2005). "The authors thus concluded that the upregulation of EGFR expression, but not oncogenic H-Ras, played a key role in developing tumour-invasive phenotype in T24 cells." (PMID 15611796, 2005). "In tumour cell lines, the sensitivity to several chemotherapeutic agents and radiotherapy was significantly modified by EGF or EGFR expression levels." (PMID 15213712, 2004). "Other studies that considered cell lines in culture have shown that indeed not all tumor cells respond to inhibition of ErbB receptors, despite exhibiting aberrant EGFR and/or ErbB2 expression." (PMID 15305194, 2004). "In a phase I/II pharmacodynamic trial in patients with metastatic colorectal cancer, gefitinib produced loss of immunohistochemical staining for activated EGFR, phosphorylated Akt and phosphorylated ERK in some but by no means all tumour biopsies." (PMID 15150574, 2004). "There appears to be no simple association between the level of EGFR1 expression and the clinical activity of EGFR TKIs; high EGFR expressing tumours do not constitute a group that is intrinsically more sensitive." (PMID 15150574, 2004). "Abnormal expression of PTK genes, such as insulin-like growth factor receptor (IGF-IR), epidermal growth factor receptor (EGFR), focal adhesion kinase (FAK), or the proto-oncogenes RET and NyK/mer, has been shown to correlate with progression in a variety of tumours." (PMID 12698188, 2003). "To shed light on the signalling pathways influenced by EGFR-TK inhibition, we investigated time-dependent alterations of the phosphorylation of ERK1/2 and p38 MAPK, which are members of the MAPK family known to be involved in EGFR signalling in non-NE tumours." (PMID 14583782, 2003). "Their overall survival was significantly longer (P=0.004) than that of patients with either EGFR-negative tumours or with mainly cytoplasmic staining." (PMID 14520458, 2003). "Levels of EGF and TGF-alpha did not correlate with levels of EGF receptor (EGFR) as determined by a radioligand binding method but levels of TGF-alpha > 10 ng gm-1 of tumour tissue did correlate with EGFR positivity defined using immunohistochemistry." (PMID 8605103, 1996).
tumor (continued). "In most cases the level of EGFR on the tumours from which the cell lines were derived has not been determined, nor have EGFR levels been determined for xenograft tumours from the cell lines." (PMID 8080726, 1994). "There was no statistical difference between degree of differentiation of the tumour and the presence of the EGFR nor between stage of the disease and EGFR presence." (PMID 1931614, 1991). "Coexpression of TGF alpha and EGFR was observed in 28% of the carcinomas, and significantly more commonly in ER negative tumours (P = 0.01)." (PMID 2331446, 1990). "In our cohort, EGFR-inhibiting antibodies may have been used alone or combined with chemotherapy to enhance response in inoperable, locally advanced RAS- and BRAF-wildtype tumours." (PMID 41511558, 2026). "Mechanistically, we demonstrated that EGFR‐driven upregulation of CD73 promotes adenosine accumulation, an immunosuppressive factor that impairs DC maturation, thereby weakening their ability to prime CD8+ T cells and initiate robust anti‐tumor immune responses." (PMID 41144813, 2026). "Additionally, tumor samples from one patient (Patient #1) were also snap-frozen at the time of collection, allowing for immunoblot analysis, which independently suggested the upregulation of LAPTM4B following the development of EGFR-TKI resistance." (PMID 41362742, 2026). "The authors concluded that inhibition of the EGFR/HER2 signalling pathway suppressed PD-L1 and released immunosuppressive cytokines, suggesting that EGFR/HER2 inhibition may create a more favourable milieu for tumour immunotherapy." (PMID 40362630, 2025). "However, macrophage-induced T-cell suppression within the tumor microenvironment can diminish the therapeutic impact of osimertinib, while the establishment of an immunosuppressive TME facilitates the development of resistance to EGFR-TKIs." (PMID 40003951, 2025). "Thus, further in vivo studies are needed, as the inhibition of both EGFR and CD73 affects cells in the tumor microenvironment and could potentially enhance anti-tumor immunity." (PMID 40191718, 2025). "The interaction between E-cadherin and EGFR (the CDH1-EGFR axis) was observed between the tumor core, boundary, and normal regions, which might lead to a significant increase in the proliferation of tumor cells via activation of the MEK/ERK signaling pathway." (PMID 41147013, 2025). "sEVs-derived from EGFR-overexpressed CAL27 cells (CAL27Hi-EGFR) not only significantly promoted the formation of tube-like structures of vascular endothelial cells, but also significantly increased the intra-tumor microvessel density in murine OSCC models, resulting in more rapid tumor growth." (PMID 39816681, 2025). "Given that AC-like cells are characterized by EGFR amplification/overexpression, which regulates VEGF expression, the enrichment of AIMP2 in this subtype may explain a possible mechanistic link between AIMP2 expression and the tumor's angiogenic profile." (PMID 40874786, 2025). "Moreover, increased UCK2 levels in HCC have been shown to promote tumor growth and metastasis by activating critical oncogenic signaling pathways, including STAT3, Wnt/β-catenin, and EGFR-AKT, whereas UCK2 knockdown significantly suppresses tumor cell proliferation." (PMID 41357200, 2025). "Additionally, to verify that tumor heterogeneity isn't altered by the enrichment, we assessed the expression of two cellular markers, EGFR and N‐Cadherin, in the original MPE sample and compared it to the tumor cell‐enriched sample following two rounds of CD45+ cells depletion." (PMID 40525275, 2025). "Thus, inhibiting of EGFR- and VEGF-A pathways with a BsAb may provide synergistic anti-tumor activity." (PMID 40969763, 2025). "In contrast, EGFR and EpCAM levels did not significantly differ across tumor grades." (PMID 40806559, 2025). "These association results suggest that the response to EGFR-TKI and ICI therapies may not depend on a single tumor characteristic or a specific tumor cell type." (PMID 39833943, 2025).
tumor (continued). "Similarly, a study with panitumumab-IRDye800CW found EGFR expression did not directly correlate with the tumor-to-background fluorescent signal ratio, due to factors like tumor vascularity and probe penetration affecting fluorescence beyond receptor levels." (PMID 40563608, 2025). "In summary, YBX1 promotes tumor progression through its transcription factor activity, exerting its effects via various downstream targets such as MUC1, CDC25a, NANOG, Kindlin-2, G3BP1, AURKA, SPP1, the EGFR-RAS-MAPK axis, CORO1C, among others, depending on the specific tumor type." (PMID 40799245, 2025). "Notably, patients who did not achieve early tumor shrinkage had worse outcomes with anti-EGFR therapy than with bevacizumab." (PMID 40280867, 2025). "The lesion did not cluster with other EGFR‐KDD neoplasms of soft tissue previously reported." (PMID 40178433, 2025). "However, several studies have since demonstrated a key role of HER3 in the activation of the PI3K/AKT signalling pathway in EGFR, HER2, and the hepatocyte growth factor receptor, MET, addicted tumours, and in particular, resistance to HER inhibitors such as cetuximab." (PMID 40940907, 2025). "EGFR inhibitor erlotinib could suppress the promotion of STARD4 on the progression of HCC, which further reinforced the idea that STARD4 exerts tumor-promoting effects and enhances the resistance to lenvatinib through activation of EGFR/PI3K/AKT pathway in HCC cells." (PMID 40831538, 2025). "Furthermore, IF staining of human GBM tissues revealed that LAIR1+ cells were predominantly CD45+, with no significant overlap with EGFR-expressing tumor cells, a marker in most GBMs." (PMID 40591413, 2025). "In contrast, EGFR-TKIs like gefitinib, erlotinib, lapatinib, afatinib, and dacomitinib inhibit the intracellular tyrosine kinase domain of EGFR, thereby preventing downstream signaling pathways, such as PI3K/AKT and MAPK/ERK, which drive tumor proliferation and survival." (PMID 40864738, 2025). "Transfer of EGFR-Engineered CD8+ lymphocytes in mice bearing B16-OVA (melanoma murine cell lines) and PM299L (hepatocarcinoma cell lines) tumors, led to increased IFN-γ production and delayed tumor growth, respectively, suggesting their potential anti-tumor activity." (PMID 39966897, 2025). "Initially, activated EGFR signaling, via the downstream Extracellular Regulated Protein Kinases (ERK) pathway, not only promotes the secretion of the VEGF ligand but also upregulates the expression of VEGF receptors on the surface of the tumor cells themselves." (PMID 41158851, 2025). "Additionally, we find that PSMA Ab, EGFR Ab, or PSMA.CAR10.3 increase in vitro phagocytosis of Myc-CaP cells expressing PSMA or EGFR by p50-IMC-derived macrophages, including in M2-promoting IL-4, which is a component of the immune-suppressive tumor microenvironment." (PMID 39904797, 2025). "Our data that targeting HELDR-activated KAT7 or targeting HELDR by ASOs augments anti-GBM activity by Erlotinib validated our observation that the previously uncharacterized HELDR-KAT7 axis promotes EGFR-driven GBM tumor malignancy independent of EGFR signaling." (PMID 40678238, 2025). "Upregulated by epidermal growth factor receptor (EGFR)/the wingless-related integration site (Wnt) signaling, LINC00973 functions as a ceRNA to sequester miR-216b and miR-150, leading to elevated expression of complement inhibitors CD55 and CD59 on tumor cells." (PMID 41409273, 2025). "It has been shown that patients without EGFR‐TKIs benefit more from immunotherapy compared with TKI experienced, since EGFR‐TKIs foster the TME associated with tumor immune escape via the innate immune signaling pathway of type I IFNs or upregulate innate immune checkpoint CD24." (PMID 40859900, 2025). "Essentially, EGFR TKIs could already inflict the effects NSAIDs might have on the tumor cell, which would explain the lack of survival benefits found in our study." (PMID 40650440, 2025).